ZNF84 (zinc finger protein 84)
Description:
May be involved in transcriptional regulation.
Synonyms: HPF2
Tractability: PROTAC: UniProt records ubiquitination sites on it; ubiquitination databases record sites on it.
Gene: Protein-coding gene on chromosome 12 (133,037,262 to 133,063,304, forward strand). Ensembl gene ENSG00000198040.
Subcellular location: Nucleus
Subcellular location (Human Protein Atlas): Nucleoplasm
Gene Ontology:
Molecular function: protein binding; DNA binding; zinc ion binding
Biological process: regulation of DNA-templated transcription
Cellular component: nucleoplasm; nucleus
Genetic constraint (gnomAD): Loss-of-function variants: 12 observed, 17.17 expected, observed/expected ratio (o/e) 0.7, 90% interval 0.45 to 1.13. The upper end of that interval is the gene's LOEUF score, 1.13, which puts it in group 4 of 6, group 1 being the genes least tolerant of losing a copy. Missense variants: 859 observed, 924.6 expected, observed/expected ratio (o/e) 0.93, 90% interval 0.88 to 0.98. Synonymous variants: 347 observed, 306.67 expected, observed/expected ratio (o/e) 1.13, 90% interval 1.04 to 1.24.
Homologues: Orthologues: chimpanzee ZNF84 (99% identical), macaque ZNF84 (99% identical), pig ZNF84 (90% identical), dog ZNF84 (89% identical), rabbit ZNF84 (88% identical), guinea pig ZNF84 (87% identical), zebrafish znf646 (25% identical), zebrafish si:dkey-89b17.4 (25% identical), zebrafish znf576.1 (24% identical), Drosophila melanogaster CG18011 (22% identical), Drosophila melanogaster CG30020 (17% identical), Drosophila melanogaster az2 (16% identical), and 11 more. Paralogues in human: ZNF184 (49% identical), ZNF160 (49% identical), ZNF420 (49% identical), ZNF91 (48% identical), ZNF569 (45% identical), ZNF208 (45% identical), ZNF729 (45% identical), ZNF99 (44% identical), ZNF594 (44% identical), ZNF107 (44% identical), ZNF347 (44% identical), ZNF845 (42% identical), and 24 more.
Diseases named in the same sentence as ZNF84 in open-access papers:
ZNF84 is named in the same sentence as 7 diseases in open-access papers, as found by Europe PMC text mining. Sharing a sentence is not in itself a finding about the gene and the disease. The quoted sentences say what the papers report.
cervical cancer (1 paper, 2021). A primary or metastatic malignant neoplasm involving the cervix. "Accordingly, a previous study reported that ZNF84 expression in cervical cancer samples was higher than in surrounding healthy tissue—and that it correlated with tumor size." (PMID 33925586, 2021).
colon cancer (1 paper, 2021). "We found that high expression of ZNF84 was associated with shorter survival of colon cancer patients." (PMID 33925586, 2021). "Intriguingly, we observed a reverse correlation between the level of ZNF84 expression and survival rate of colon cancer patients." (PMID 33925586, 2021). "To examine if ZNF84 expression impacts on disease outcome, we analyzed TCGA data from 275 colon cancer patients and found a strong correlation between ZNF84 expression and overall survival." (PMID 33925586, 2021).
escherichia coli infection (1 paper, 2026). Infection with the organism Escherichia Coli. "ZNF84 showed negative enrichment in lysosomal function, cytoskeletal regulation, and immune-related modules such as FC gamma R–mediated phagocytosis and pathogenic Escherichia coli infection." (PMID 41601671, 2026).
cancer (2 papers, 2021). A tumor composed of atypical neoplastic, often pleomorphic cells that invade other tissues. "ZNF84 deficiency was also associated with transcriptomic changes in genes governing various cancer-relevant processes e.g., mitosis." (PMID 33925586, 2021). "In order to pursue the role of ZNF84 in cancer, single cell analysis of ZNF84/p21 level together with cell fate tracing would be desirable." (PMID 33925586, 2021). "In summary, from the results presented here, a model emerges of ZNF84 as a protein impacting cancer cells’ response to chemotherapy and affecting cancer progression." (PMID 33925586, 2021). "The implications of low ZNF84 level for cancer cells (e.g., their aggressiveness and treatment response) is an important question." (PMID 33925586, 2021). "In summary, our results indicate that ZNF84 is involved in genotoxic stress response via regulation of p21 expression, in cancer cells originating from different tissues and with various genetic backgrounds." (PMID 33925586, 2021). "As we have observed that upon ZNF84 silencing many cancer cell lines exhibit cell cycle perturbation, depletion of some markers of senescence and, perhaps most intriguingly, decreased DNA damage signaling, we were interested how ZNF84 deficiency would affect cancer cell fitness." (PMID 33925586, 2021).
tumor (2 papers, 2021).
ZNF84 also shares sentences with these, for which no sentence is quoted: Infertility (1 paper); lung adenocarcinoma (1).